MYCN (MYCN proto-oncogene, bHLH transcription factor)
Diseases named in the same sentence as MYCN in open-access papers (continued):
Sharing a sentence is not in itself a finding about the gene and the disease.
neuroblastoma (continued). "Only the neuroblastoma-amplified gene (NAG), DEAD (Asp-Glu-Ala-Asp) box polypeptide 1 (DDX1), MYCN and hypothetical protein LOC81553 (FAM49A) are present in this region between 15.5 × 106 bp and 17.5 × 106 bp from 2pter." (PMID 17601344, 2007). "PRKCQ-AS1 is a superenhancer-driven long noncoding RNA that promotes MYCN-nonamplified neuroblastoma progression by interacting with the MSI2 protein to stabilize BMX mRNA and increase ERK phosphorylation." (PMID 41602364, 2026). "Treatment with FGFR inhibitors impaired proliferation and pathway activation in FGFR1N546K-expressing Ba/F3 and patient-derived FGFR1N546K-mutant neuroblastoma cells and inhibited tumor growth in FGFR1N546K;MYCN transgenic mice and in a chemotherapy-resistant, patient-derived xenograft mouse model." (PMID 41678281, 2026). "Although survival extension in xenograft models supports target engagement, PHGDH inhibition in MYCN-amplified neuroblastoma models primarily induces cytostatic effects rather than cytotoxicity, and tumors rapidly develop resistance through metabolic rewiring." (PMID 41486146, 2026). "Regarding NETs, the transcriptional differences were less marked but with a strong upregulation of the MYCN program in high‐grade NETs, a known oncogene in neural crest‐derived tumors like neuroblastomas, but never reported in NETs." (PMID 41416936, 2026). "Importantly, we have proved that targeting KLHL37 leads to remarkable suppression of MYCN-amplified neuroblastoma in vitro and in vivo, indicting that KLHL37 is an appropriate therapeutic target for neuroblastoma." (PMID 40493396, 2025). "With 50%–70% radiochemical yield and >95% radiochemical purity, 191Pt-MYCN-PIP achieved ∼10-fold higher uptake and DNA-binding in MYCN-amplified vs. non-amplified neuroblastoma cells, and reduced MYCN expression in vitro." (PMID 41018941, 2025). "The Wnt ligand signature was enriched in neuroblastomas without MYCN amplification in both the TARGET NBL and St Jude PCGP cohorts (Supplementary 2b)." (PMID 40962798, 2025). "NIPBL mRNA expression was not significantly different between MYCN-amplified and non-amplified neuroblastoma patients." (PMID 40867243, 2025). "By supporting MYCN expression and enhancer occupancy, NIPBL facilitates the repression of neuronal differentiation programs driven by MYCN, thereby inhibiting the differentiation of neuroblastoma." (PMID 40867243, 2025). "PRKCQ‐AS1 or MSI2 knockdown reduces, while its overexpression enhances, BMX mRNA stability and expression, ERK protein phosphorylation and MYCN nonamplified neuroblastoma cell proliferation." (PMID 40103284, 2025). "In this study, our RNA sequencing data identified PRKCQ‐AS1 as the lncRNA most differentially highly expressed in MYCN nonamplified neuroblastoma cell lines." (PMID 40103284, 2025). "Here PRKCQ‐AS1 is identified as the lncRNA most overexpressed in MYCN nonamplified, compared with MYCN‐amplified, neuroblastoma cell lines." (PMID 40103284, 2025). "Enhanced computed tomography revealed a urachal tumor, later confirmed pathologically as neuroblastoma without MYCN amplification." (PMID 40254724, 2025). "We screened these polyphenols for their cytotoxic and cytostatic properties against two subtypes of human neuroblastoma cell lines: IMR32 (MYCN-amplified) and SH-SY5Y (MYCN non-amplified)." (PMID 41304961, 2025). "In the current study, we have found that PRKCQ‐AS1 knockdown reduces MYCN nonamplified neuroblastoma cell proliferation, considerably inhibits clonogenic capacity, suppresses tumor progression and improves survival in two mouse models." (PMID 40103284, 2025). "We selected two neuroblastoma cell lines (SK-N-BE2c: MYCN-amplified, SK-N-AS lacking MYCN amplification) in which to evaluate the feasibility of site-specific cytokine transgene integration." (PMID 41366257, 2025). "Track plots showed the SE_513 super‐enhancer in MYCN nonamplified but not MYCN‐amplified neuroblastoma cell lines." (PMID 40103284, 2025).
neuroblastoma (continued). "To further validate our in vitro findings in a clinically relevant context, we analyzed MYCN non-amplified neuroblastoma patient-derived organoids." (PMID 40513779, 2025). "The data suggests that PRKCQ‐AS1 is overexpressed in MYCN nonamplified neuroblastoma cells due to transcriptional super‐enhancers." (PMID 40103284, 2025). "In this study, we reveal PA2G4 as a critical cofactor for both MYCN and c-MYC in neuroblastoma." (PMID 41002386, 2025). "Neuroblastoma derives from embryonic neural crest cells, and in NB tumors that harbor amplification of the proto-oncogene MYCN, a transcriptional core regulatory circuitry (CRC) that includes MYCN, HAND2, ISL1, PHOX2B, GATA3, and TBX2 promotes tumorigenesis." (PMID 40766465, 2025). "Differential gene expression analysis of lncRNAs revealed PRKCQ‐AS1 as the top lncRNA overexpressed in the MYCN‐nonamplified neuroblastoma cells (log2Fold change = −7.13, p value = 4.15e−12, false discovery rate = 2.40e−09)." (PMID 40103284, 2025). "To ensure that the observed toxicity is cancer cell-specific, we then compared the cell viability between hTERT RPE-1 (hTERT-immortalized retinal pigment epithelial) cells and 6 neuroblastoma cells with or without MYCN overexpression." (PMID 40701975, 2025). "To systematically uncover the relevance of KLHL family proteins to N-Myc, we first assessed the effect of the KLHL family on the proliferation of MYCN-amplified and non-MYCN-amplified neuroblastoma cells using an siRNA library targeting KLHLs." (PMID 40493396, 2025). "Our analysis of ChIP‐seq databases of MYCN‐amplified and c‐MYC‐expressing neuroblastoma cells, suggests that both MYCN and c‐MYC can directly bind the promotor of ATP13A3, though each at different regions, and thus may regulate ATP13A3 mRNA levels." (PMID 39981745, 2025). "We observed that ATP13A3 silencing in both MYCN‐amplified (KELLY) and non‐MYCN‐amplified (SH‐SY5Y) neuroblastoma cells significantly attenuated cell growth and that this was a dose‐dependent effect as less effective silencing was associated with less pronounced effects on growth inhibition." (PMID 39981745, 2025). "We investigated the relevance of PRMT5 and E2F1 in neuroblastoma (NB) and found that elevated expression of PRMT5 and E2F1 occurs in poor prognosis high‐risk disease and correlates with an amplified Myelocytomatosis viral‐related oncogene, neuroblastoma‐derived (MYCN) gene." (PMID 39021294, 2025). "Taken together, the data suggest that the lncRNA PRKCQ‐AS1 is significantly overexpressed in MYCN nonamplified, compared with MYCN‐amplified, neuroblastoma cells." (PMID 40103284, 2025). "The current International Neuroblastoma Risk Group (INRG) stratification system relies on static indicators such as age, stage, and MYCN amplification, yet it fails to predict treatment responses in real time." (PMID 41267975, 2025). "Taken together, the data suggest that PRKCQ‐AS1 overexpression in MYCN‐nonamplified neuroblastoma cells is due to a transcriptional super‐enhancer, and that PRKCQ, in contrast, is not significantly regulated by transcriptional super‐enhancers." (PMID 40103284, 2025). "RT‐PCR also confirmed PRKCQ‐AS1 to be highly expressed in MYCN‐nonamplified, compared with MYCN‐amplified, human neuroblastoma cell lines." (PMID 40103284, 2025). "The effect was particularly pronounced in MYCN non-amplified neuroblastoma, highlighting a potential therapeutic window." (PMID 41515404, 2025). "In contrast, MYCN-amplified cells were particularly sensitive to RTA-408 treatment, as evidenced by an inhibition rate of 93.2% ± 11.0%, suggesting that RTA-408 shows pronounced therapeutic selectivity and potency in neuroblastoma cells driven by Myc." (PMID 40493396, 2025). "Classically cold MYCN‐driven neuroblastoma predominantly present without a functional cGas/STING axis, underlining, that taming this pathway is crucial during MYCN‐driven tumorigenesis." (PMID 40488968, 2025).
neuroblastoma (continued). "Alternative models that produce neuroblastoma in mice include simian virus 40 T-antigen expression and dopamine β-hydroxylase (DBH) promoter-driven Cre expression leading to overexpression of MYCN or LIN28B." (PMID 40874091, 2025). "Across neuroblastoma cell lines, the subtype-specific difference in MYCN and MYC are not significant." (PMID 39825754, 2025). "Recent results on Neuroblastoma cell lines revealed a class of MYCN amplicons that lacked key local enhancers of MYCN, but hijacked distal fragments containing previously discovered super-enhancers known to mediate Neuroblastoma progression." (PMID 41422275, 2025). "In summary, this study identifies PRKCQ‐AS1 as the lncRNA most overexpressed in MYCN nonamplified, compared with MYCN‐amplified, neuroblastoma cell lines, and transcriptional super‐enhancers as the factor responsible for PRKCQ‐AS1 overexpression." (PMID 40103284, 2025). "Next, NB69 MYCN‐nonamplified neuroblastoma cells were transfected with an empty vector or PRKCQ‐AS1 expression construct." (PMID 40103284, 2025). "In neuroblastoma, miR-221 enhances mycn protooncogene, bhlh transcription factor (MYCN) oncoprotein levels by targeting Nemo-like kinase (NLK), a negative regulator of MYCN; high miR-221 expression correlates with advanced disease and poor prognosis." (PMID 41369385, 2025). "Since MYCN may have a stronger impact on the transcriptional regulation of ODC1 than of ATP13A3, neuroblastoma cells may be more dependent on biosynthesis and less dependent on polyamine uptake when MYCN is expressed." (PMID 39981745, 2025). "To investigate the impact of genetic background on tumor biology, we established xenograft models using both MYCN-amplified and non-amplified neuroblastoma cell lines." (PMID 41228227, 2025). "Conversely, targeting MYCN with Cas9D10A was well-tolerated in MYCN non-amplified (SH-SY5Y) and MYCN non-amplified, non-neuroblastoma (HEK293T) cell lines." (PMID 40456709, 2025). "Consistent with this, JNK activity has been implicated in migration, invasion, and stress-induced apoptosis in both MYCN-amplified and MYCN-non-amplified neuroblastoma models." (PMID 41465323, 2025). "Human neuroblastoma cell lines also show decreased growth and maturation when treated with DFMO, although some cell lines without MYCN amplification show a reduced response compared to those with MYCN amplification." (PMID 40004600, 2025). "Harmine treatment resulted in dose- and time-dependent caspase-mediated apoptosis in MYCN non-amplified but especially in MYCN-amplified neuroblastoma cells." (PMID 39714760, 2025). "At the genetic level, the most extensively studied genetic alteration in neuroblastoma is MYCN amplification, which, even in the absence of other significant adverse prognostic factors, is sufficient to categorize patients as high-risk." (PMID 39720601, 2025). "Given that MYCN transcriptionally activates MIR17HG in neuroblastoma and medulloblastoma, we examined the expression levels of the miR-17–92 cluster across a panel of FP-RMS lines with variable expression of P3F and MYCN." (PMID 41473312, 2025). "Our RNA sequencing has identified PRKCQ‐AS1 as the lncRNA most overexpressed in MYCN nonamplified, compared with MYCN‐amplified, human neuroblastoma cell lines." (PMID 40103284, 2025). "Although we did not evaluate G6PD gene expression in MYCN-amplified neuroblastoma cells, it was reported that MYCN levels were correlated with altered expression of proteins involved in enhanced glycolysis and increased oxidative phosphorylation." (PMID 41291487, 2025). "In this study, we used two neuroblastoma cell lines: CHLA15 (MYCN non-amplified but MYC-overexpressing) and LAN5 (MYCN-amplified) to investigate the cytotoxic effects of pomiferin and osajin." (PMID 40332068, 2025). "Subsequent work showed that FOXR2 stabilizes MYCN protein in non-MYCN-amplified neuroblastoma patients, and it presumably also stabilizes non-cMYC-amplified cancers." (PMID 40075567, 2025).
neuroblastoma (continued). "A previous study has shown that ADC histogram features differ between MYCN-amplified and non-amplified neuroblastomas." (PMID 41228227, 2025). "In MYCN-amplified neuroblastoma, MP1 treatment led to marked destabilization of MYCN protein, accompanied by decreased Mcl-1 expression and induction of autophagic flux, as reflected by increased LC3II accumulation, a widely used marker of autophagosome formation and autophagic activity." (PMID 41149606, 2025). "Neuroblastoma patients aged less than one year with stage 4S without MYCN amplification are more likely to experience spontaneous regression of their tumor." (PMID 41189817, 2025). "Similarly, in neuroblastoma, ASCL1 acts as a pioneer factor where it then recruits and cooperates with MYCN at genomic loci to drive adrenergic cell fate conversion." (PMID 40498845, 2025). "MYCN and c-MYC are critical driver oncogenes in several childhood cancers, including neuroblastoma." (PMID 41002386, 2025). "In relation to ATP13A3 however, high ATP13A3 expression levels negatively correlate with survival of neuroblastoma patients, irrespective of MYCN status." (PMID 39981745, 2025). "Here, the authors report two novel nonsense mutations in the ATRX gene in two unrelated older than 18 months of age children with advanced MYCN non-amplified neuroblastoma." (PMID 40286729, 2025). "This contributed to an increased chemoresistance to doxorubicin in MYCN-amplified neuroblastoma cell lines compared with non-MYCN amplified lines." (PMID 40426729, 2025). "Our findings therefore identify PRKCQ‐AS1 and MSI2 as important novel co‐factors for MYCN nonamplified neuroblastoma tumorigenesis, and provide novel targets and a novel therapeutic agent for the treatment of MYCN nonamplified neuroblastoma." (PMID 40103284, 2025). "In this study, we compared the multiple inhibitory activities of selected dietary polyphenols and their combinations on key metabolic and signaling pathways in two neuroblastoma cell lines with and without MYCN amplification." (PMID 41304961, 2025). "In general, the initial management of an L2 neuroblastoma without MYCN amplification involves chemotherapy with or without surgical intervention or, in selected cases, a watchful waiting approach." (PMID 40520658, 2025). "In this study, 37 tumor samples from Brazilian patients with stages I to IV MYCN non-amplified neuroblastoma, according to the International Neuroblastoma Staging System (INSS), were analyzed using the panel OncomineTM Childhood Cancer Research Assay." (PMID 40286729, 2025). "The authors found two older children (NB1 and NB2) with advanced MYCN non-amplified neuroblastoma carried each one of the two following novel nonsense ATRX variants (p.Gln1670* or p.Glu1984*)." (PMID 40286729, 2025). "These NIPBL-bound MYCN peaks are highly enriched for motifs of core regulatory circuitry (CRC) transcription factors such as GATA3, PHOX2A, HAND1, and HAND2, which contribute to the maintenance of the neuroblastoma oncogenic cell identity." (PMID 40867243, 2025). "Taken together, the data demonstrate that PRKCQ‐AS1 promotes MYCN‐nonamplified neuroblastoma cell proliferation." (PMID 40103284, 2025). "This dual inhibition results in MYCN inhibition, cell cycle arrest, apoptosis induction, and neuronal differentiation promotion, particularly in MYCN-amplified neuroblastoma cells compared with their non-MYCN amplified counterparts." (PMID 39802403, 2025). "Moreover, MYCN and MYC directly influence tumor proliferation and tumorigenesis through BMI1 in human neuroblastomas." (PMID 40862719, 2025). "In addition, we genetically modified four MYCN-amplified neuroblastoma cells (SKNBE2, NB5, NBLS, and IMR-32) to express three different doxycycline-inducible shRNA that knock downed MYCN protein levels." (PMID 38837897, 2024).
neuroblastoma (continued). "This suggests that patients with MYCN-amplification might benefit the most from anti-GD2 treatment which significantly activates PHLDA1 expression, at least in IMR-32 neuroblastoma cell line." (PMID 38495105, 2024). "To further explore the value of assessing intrinsic disorder for the entire TRB variable region, we aimed to identify OS distinctions for another (relatively) non-immunogenic cancer type: MYCN amplified neuroblastoma." (PMID 39519243, 2024). "In an unbiased attempt to identify subtypes within MYCN non-amplified neuroblastomas, we applied consensus clustering to both train and test groups based on 5792 variable genes (top 50% median absolute deviation)." (PMID 38553589, 2024). "Here we provide bioinformatics and experimental evidence for universally high levels of AF1q gene and protein expression in MYCN amplified and MYCN non-amplified neuroblastoma tumors and tumor-derived cell lines." (PMID 38413795, 2024). "Taken together, these results suggested that a “MYCN” signature in subgroup 2 is potentially induced by AURKA overexpression in MYCN non-amplified neuroblastomas." (PMID 38553589, 2024). "Further, acetylation-independent activation of gene regulation by SAGA has been demonstrated, and our studies do not rule out an acetyltransferase-independent SAGA function in neuroblastoma, perhaps due to interactions with transcription factors such as MYCN." (PMID 38820154, 2024). "Despite the extensive study of MYCN-amplified neuroblastomas, there is a significant unmet clinical need in MYCN non-amplified cases." (PMID 38553589, 2024). "In this study, using tumour expression data and ConsensusClusterPlus, we demonstrate that MYCN non-amplified neuroblastomas are heterogeneous and can be further classified into 3 subgroups based on their transcriptional profiling." (PMID 38553589, 2024). "Together, these data indicate that ZIKV therapy offers a remarkable survival advantage across an array of neuroblastoma tumors, regardless of MYCN amplification or status as pretreatment versus posttreatment recurrent cancer." (PMID 38214542, 2024). "To further test the effect of high DDX1 expression in cancer cells, we selected human neuroblastoma cell lines harboring MYCN amplifications, not including DDX1 and introduced a doxycycline-inducible DDX1 expression vector." (PMID 38197697, 2024). "When MYCN amplified and non-amplified neuroblastomas were separated, both were still among the highest expressing cancer cell lines." (PMID 38413795, 2024). "Indeed, the current study showed that the PRMT5 inhibitor, JNJ-64619178, is effective against neuroblastoma cell lines and demonstrated SNRPD3- and MYCN-dependency." (PMID 38049564, 2024). "CD9 encodes a tetraspanin protein whose high expression inhibits neuroblastoma development and correlates with a lack of MYCN amplification." (PMID 38398114, 2024). "Our previous work showed an EGF-induced reduction in CD levels in MYCN-not-amplified SH-SY5Y neuroblastoma (NB) cells." (PMID 38611021, 2024). "Based on this, it was suggested that the main contribution to the higher signal in MYCN-amplified neuroblastoma cells compared to MYCN-non-amplified neuroblastoma cells is not due to an increased copy number of the super-enhancer sequence." (PMID 38542080, 2024). "Opaganib inhibited cell proliferation regardless of the MYCN gene status of the neuroblastoma cells." (PMID 38730731, 2024). "Indeed, the PRMT5 inhibitor, JNJ-64619178, reduced cell viability and SNRPD3 methylation in neuroblastoma cells with high SNRPD3 and MYCN expression." (PMID 38049564, 2024). "HLA class I expression was significantly lower in tumor than non-tumor cells, particularly in those with high MYCN expression, highlighting neuroblastoma’s low immunogenicity." (PMID 38181797, 2024).